BSG (basigin (Ok blood group))
Diseases named in the same sentence as BSG in open-access papers (continued):
Sharing a sentence is not in itself a finding about the gene and the disease.
tumor (continued). "Validation analysis confirmed the up-regulation of model genes, including AKR1B10, ARL6IP4, ATP6V0B, and BSG in tumor tissues." (PMID 38913193, 2024). "Then, we also observed the high expression of BSG and its positive relation to advanced stages and tumor metastasis." (PMID 33654226, 2022). "BSG acts as a chaperone to MCT1 and is necessary for its proper functioning, as BSG downregulation leads to disruption of lactate transport and decreases proliferation of tumour cells." (PMID 35054026, 2022). "The expression of PPIA and BSG was positively correlated in all 22 tumor types analyzed, indicating that the CypA/CD147 interaction plays a crucial role in cancer development." (PMID 36012604, 2022). "Growing basic evidences have indicated that basigin (BSG, also named TCSF, CD147, EMMPRIN) is a transmembrane-type glycoprotein that is strongly expressed on the cell membranes of several tumor cells." (PMID 33654226, 2022). "It is also reported that T cells and NK cells carrying a chimeric antigen receptor that recognizes BSG is detrimental to the tumor cell lines in vitro." (PMID 35646943, 2022). "In our cohort, we also confirmed the mRNA expression of BSG was upregulated in HCC specimens and had a potential diagnostic in distinguishing HCC specimens from non-tumor specimens." (PMID 33654226, 2022). "To validate the clinical significance of the CypA/CD147 interaction, we analyzed the expression levels of PPIA and BSG genes encoding CypA and CD147, respectively, in a wide range of tumor types using The Cancer Genome Atlas (TCGA) database." (PMID 36012604, 2022). "In fibroblasts, the mRNA level of EMMPRIN (BSG), which increases the MMPs production in pathological conditions (i.e., tumor invasion in cancer), was decreased by Exo treatment by 1.2-fold." (PMID 34207905, 2021). "The important role played by BSG in tumor cell invasion made this gene an excellent target for cancer treatment." (PMID 32891152, 2020). "BSG was thought to enhance tumor metastasis, angiogenesis, and drug resistance through its association with various proteins." (PMID 32151082, 2020). "Recently, researchers have identified that BSG expression regulates tumor cell glycolysis, resulting in the progression of TC." (PMID 32891152, 2020). "BSG, also named ECM metalloproteinase inducer (EMMPRIN), is expressed on the surface of tumor cells and induces fibroblasts to synthesize matrix metalloproteinases." (PMID 29559981, 2018). "We first selected basigin (CD147), a product of the BSG gene depicted in the tumor invasion network." (PMID 29899869, 2018). "BSG expression correlated with the histological type of tumours, grade of cancers, tumour progression and recurrence and patient survival." (PMID 26099350, 2016). "BSG (CD147, EMMPRIN) is an inducer of tumor cell associated MMPs, including MMP1, MMP2, MMP3, and MMP9." (PMID 26769849, 2016). "Recent studies from our group showed that BSG knockout in colon, glioma, and lung cancer cell lines promoted tumour proliferation through metabolic reprogramming, but without any significant change in the expression levels of MMPs compared to parental cells." (PMID 26099350, 2016). "As MMP2 and MMP9 are usually associated with tumour progression in a BSG-dependent way, we investigated their expression in a series of BASIGIN-positive human tumour cells." (PMID 26284589, 2015). "We observed that MCT1, MCT4 and BSG were significantly overexpressed in tumour samples when compared to adjacent non-tumour tissue." (PMID 25894929, 2015). "The effect of BASIGIN knockout on tumour microenvironment regulation, and in particular on fibroblasts activation, was tested in vitro on co-cultures of tumour cells lines (wild type versus BSG-null cells) with human or mouse embryonic fibroblasts." (PMID 26284589, 2015).
tumor (continued). "The impact of BASIGIN on MMPs production by tumour cell lines was first evaluated by analysing the MMP2 and MMP9 activities in CM from wt versus BSG−/− tumour cell lines alone, or co-cultured with fibroblasts." (PMID 26284589, 2015). "In the absence of a specific pharmacological inhibitor of MCT4, and taking into account the interdependency between MCTs and their chaperone, we decided to develop BSG-null cells to further explore the role of MCTs in targeting glycolysis and tumour growth." (PMID 25894929, 2015). "BSG levels in GBM tissue were more than twice that of control indicating a contributory role in tumour progression providing a potential therapeutic target." (PMID 24728830, 2014). "A number of mitochondrial proteins with relevance to tumour pathophysiology were altered, including BSG, SNCB and three Isocitrate dehydrogenase 3 forms (IDH3A, IDH3B, and IDH3G)." (PMID 24728830, 2014). "Extracellular MMP inducer (EMMPRIN), also called CD147 or basigin (BSG), is a 55-kDa molecule expressed on the tumor cell surface that plays important roles in the up-regulation of peri-tumoral fibroblasts." (PMID 23817808, 2013). "The interaction between PPIA and BSG not only promotes tumor cell invasion as well as metastasis but may also optimize the TME by impacting extracellular matrix remodeling, thus creating conditions for immune escape." (PMID 40115255, 2025). "Previous studies showed that BSG played significant roles in tumor progression and may be a biomarker for prognosis." (PMID 38484369, 2024). "Through the volcano plot, a prominent upregulation of BSG is detected in tumor cells." (PMID 38617561, 2024). "Finally, BSG promotes tumor progression by facilitating the translocation of monocarboxylate transporters to the plasma membrane, thereby increasing the aerobic glycolysis of tumor cells." (PMID 38892056, 2024). "The inhibition of BSG can reduce the growth, migration, and invasion of tumor cells." (PMID 35646943, 2022). "As suggested by those finding, together with previous findings, BSG could be a tumor promoter in HCC." (PMID 33654226, 2022). "Via a proteomic analysis, 912 proteins were identified in MVs from pleural effusion samples of three NSCLC patients, including several tumor-associated proteins such as EGFR, KRAS, BSG/EMMPRIN/CD147, CEACAM6, CLDN1, CLDN3, and RAB family proteins (e.g., Rab1, Rab3, Rab5, Rab6, Rab11, and Rab13)." (PMID 35158999, 2022). "Furthermore, a previous study also found that the upregulated expression of BSG directly contributed to tumor angiogenesis by stimulating vascular endothelial growth factor (VEGF) production via the PI3K/AKT pathway." (PMID 32891152, 2020). "Moreover, present researchers who have studied BSG expression levels have shown that BSG plays an important part in tumor cell invasion, metastasis, and angiogenesis." (PMID 32891152, 2020). "Our previous study has reported that CD147/basigin (BSG) is highly expressed in HNSCC sphere‐forming cells compared to adherent cells, which suggest that CD147/BSG might be a predictable marker for tumor progression of HNSCC." (PMID 30421493, 2019). "ADAM12-mediated shedding of BSG could promote tumor progression by stimulating MMP activation and enabling cancer cell invasion." (PMID 31013576, 2019). "This function, based on nearly 200 studies showing a positive correlation between knockdown or ectopic expression of BSG and levels of different MMPs (1, 2, 3, 9, 11, 14 and 15), was proposed to be mediated via up-regulation of MMPs produced by fibroblasts neighbouring tumour cells." (PMID 26099350, 2016). "Moreover, BSG expression usually co-localised with MCT1/MCT4 in tumour tissues, which constitutes a prognostic marker of poor clinical outcome." (PMID 26099350, 2016). "Thus, genetic silencing studies on BSG have reported inhibition of tumour growth and increased cell death in different cancer cell lines associated with reduced, angiogenesis, MMP secretion, invasiveness and chemo-resistance." (PMID 26099350, 2016).
tumor (continued). "In fact, tumour growth increased approximately 4-fold for BSG−/− cells compared to wt cells." (PMID 25894929, 2015). "Surprisingly, BSG−/− cells generated bigger tumours than wt cells (B-black lines)." (PMID 25894929, 2015). "In addition we observed that phenformin drastically inhibited tumour growth, with a stronger impact on BSG−/− cells compared to wt cells." (PMID 25894929, 2015). "For instance, SLC16A1 and BSG, belonging to cluster 1 and playing vital roles in energy metabolism, are up-regulated in a variety of cancer types and could promote tumor growth and aggressiveness through the Warburg effect." (PMID 35580989, 2022). "BSG could also promote tumor angiogenesis via regulating MMPs and VEGF." (PMID 32891152, 2020). "However, phenformin greatly reduced the tumour burden in BSG−/− cells than in wt cells." (PMID 25894929, 2015). "Gemcitabine drug-resistant Gal-3-high tumor cells can increase the expression of CCL2 and BSG in TAFs through the Ca2+–calcineurin–NFAT pathway, thereby leading to mitochondrial oxidative phosphorylation suspension via CCL2–CCR2 cell signaling." (PMID 40600063, 2025). "To further validate the expression and clinical significance of the CypA/CD147 axis in a wide range of cancers, we performed gene expression and survival analyses of PPIA and BSG in 24 different tumor types." (PMID 36012604, 2022). "FBXO22 can reverse cisplatin resistance in tumor cells by mediating polyubiquitination and degradation of basigin (BSG, also known as CD147) through its recognition of the BSG intracellular domain." (PMID 35141150, 2021). "BSG/CD147 has been shown to induce MMPs expression in stromal as well as in tumor cells, which plays critical role in tumor invasion and metastasis." (PMID 26769849, 2016). "In parallel to MCT1/4 overexpression, CD147/BSG is also commonly up-regulated in cancers, and since 1990, more than 540 research articles have highlighted its pro-tumour role." (PMID 26099350, 2016). "As no pharmacological inhibitor of MCT4 is yet available and as previous published results showed that the major pro-tumour action of BSG is mediated through bioenergetics, namely by controlling lactate transport, we decided to knockdown both MCT4 and BSG." (PMID 25894929, 2015). "In our analysis eight new candidate tumor suppressor genes were identified, OXSR1 (3p22.2), BSG(19p13.3), NT5E(6q14.3), PLEKHG7(12q22), CMTM8(3p22.3), NETO2(16q12.1), ODZ3(4q35.1) and ERBB4(2q34)." (PMID 25551557, 2014). "Our proteomic and IF findings demonstrate that TuNEPs have enriched cell adhesion proteins BSG and ITGA2, we next investigated whether these proteins impact tumor growth." (PMID 40751052, 2025). "In contrast, other tumor areas exhibiting high expression of TMPRSS11B together with BSG and SLC16A1 were largely negative for KLF4 expression." (PMID 40508207, 2025). "MRNA expression level of BSG was the highest, followed by HSPA5 in most tumor and normal tissues." (PMID 38484369, 2024). "The box plot shows that the CD133 (PROM1) and CD147 (BSG) genes were significantly hypermethylated in tumors compared to normal tissues; inversely, their mRNA expression levels were downregulated in tumor tissues." (PMID 36498950, 2022). "Thus, the relationship between BSG expression and the three clinical parameters—AJCC stages, age, and gender—of patients was explored in neoplasms with the clinical parameter data." (PMID 35646943, 2022). "Also, it was recently shown that cholesterol-depletion induces ectodomain shedding of BSG by a disintegrin and metalloproteinase (ADAM)-10 in tumor cells." (PMID 31013576, 2019). "This pro-tumoural model placed BSG at the centre of tumour invasion but so far remains only correlative with no molecular mechanisms demonstrating how BSG or its soluble form is capable of inducing MMPs." (PMID 26099350, 2016).
tumor (continued). "Using co-cultures of either human fibroblasts or mouse embryonic fibroblasts (MEFs) and tumour cell lines we showed, in contrast to the published literature, that the disruption of BSG in tumour cells and in MEFs does not modify the production of MMPs." (PMID 26099350, 2016). "On the other hand, treatment of human head and neck squamous cell carcinoma with the anti-BSG monoclonal antibody (CNTO3899) was found to reduce proliferation and induce caspase-mediated apoptosis of cells ex vivo, and to impair tumour growth with increased radio-sensitivity in vivo." (PMID 26099350, 2016). "Indeed, we and others have shown that targeting BSG with shRNA or deleting the BSG gene with zinc fingers nucleases (ZFNs) reduced levels of expression of MCT1/MCT4, increased the intracellular pool of lactic acid and impaired tumour growth in vivo." (PMID 26099350, 2016). "However, only BSG-null cells, independently of their LKB1 status, remained sensitive to biguanides in hypoxia in vitro and tumour growth in nude mice." (PMID 25894929, 2015). "Several proteins, for example BSG (increased in GBM), SNCB (decreased in GBM) and IDH3 (with IDH3A, IDH3G and IDH3B all decreased in GBM), did not fall into an obvious functional grouping but are pertinent to tumour pathophysiology (see “Discussion” section)." (PMID 24728830, 2014). "Besides the known tumor suppressor genes DOCK5 and PTEN, genes OXSR1, BSG, NT5E, PLEKHG7,CMTM8, NETO2, ODZ3, and ERBB4 adhered to our criteria and were qualified as novel candidate tumor suppressor genes." (PMID 25551557, 2014). "In vivo studies showed that BSG disruption did not reduce tumour growth as shown by other groups." (PMID 25894929, 2015). "A study comparing the anti-tumor activity of BSG and G. lucidum sporoderm-nonbroken (NBSG) showed that the purity of BSG was more active than that of NBSG against cancer cells including SGC-7901, HeLa." (PMID 37790044, 2023). "Generally, the DNA methylation pattern of the CD147/BSG gene promoter was low and not variable in tumor tissue, underpinning a minor impact of DNA methylation on variability of expression in ccRCC." (PMID 26384346, 2015). "Consequently, tumor cells exhibiting reverse Warburg metabolism would be supported by the absence of TMPRSS1B and thereby the lack of BSG cleavage, as seen in, e.g., T3M4 cells or in Panc1 and BxPc3 cells after knock-down of TMPRSS11B." (PMID 40508207, 2025).
cancer (419 papers, 2006 to 2026). A tumor composed of atypical neoplastic, often pleomorphic cells that invade other tissues. "This is underscored by the fact that in SLC16A1/BSG-expressing but TMPRSS11B-deficient cancer cells, the nuclear expression levels of reprogramming factors such as KLF4 are elevated, a condition identified as a hallmark of reverse Warburg cells." (PMID 40508207, 2025). "We conducted Kaplan-Meier analysis to evaluate the association between BSG expression and cancer patients’ prognoses." (PMID 38484369, 2024). "We also found that expression of the BSG protein tended to be statistically linked to cancer subtypes (p < 0.0001) based on the analysis of clinical parameters." (PMID 32891152, 2020). "In line with the shed BSG ectodomain being a potential biomarker in cancer, we found a number of cancer-associated mutations in the region harboring the ADAM12 cleavage site." (PMID 31013576, 2019). "These MMPs have also been reported to be associated with cancer progression in a BSG-dependent manner." (PMID 26284589, 2015). "Recent studies have highlighted the role of BSG isoforms in cancer biology, suggesting that individual transcript variants may have distinct functional characteristics and prognostic significance." (PMID 39006665, 2024). "Moreover, the study also investigated the association of BSG with alternative genes and immune infiltration levels in cancers, contributing to the understanding of BSG as a novel and potential biomarker for the identification and treatment of multiple cancers." (PMID 35646943, 2022). "Additionally, we assessed the mRNA expression of MCT1 and VEGF, the two proteins associated with BSG function in cancer." (PMID 35054026, 2022). "Importantly, assessment of publicly available data revealed a number of cancer-associated BSG mutations in the ADAM12 cleavage region and when tested experimentally, we found that some of the mutations alter the susceptibility to ADAM12-mediated cleavage." (PMID 31013576, 2019). "Therefore, we conducted mutation analysis of the BSG gene in pan-cancers." (PMID 38484369, 2024). "Moreover, the mutation status of BSG in cancers may affect or correlate the expression of other entry receptors." (PMID 38484369, 2024). "Looking into the structural information, BSG has been shown to function as a dimer, and the dimerization of the two BSG molecules were suggested to take place around amino acids 184–196, which is exactly at the beginning of the region harboring the identified cancer mutations." (PMID 31013576, 2019). "Indeed, deregulation of BSG has been linked to almost every type of cancer." (PMID 26099350, 2016). "While BSG1 is expressed only in the retina, BSG2 (now named BSG below) is expressed in all other tissues as well as in malignant tumors in which it is often overexpressed." (PMID 40508207, 2025). "It is important to understand the expression of BSG in different normal tissues and malignant tumors." (PMID 38484369, 2024). "In conclusion, the findings reported here add to the complexity of mechanisms whereby BSG exerts its cancer-related functions." (PMID 38892056, 2024). "In the present study, we conducted a comprehensive analysis on expression level of a novel SARS-CoV-2 receptor BSG in healthy tissues and pan-cancers." (PMID 38484369, 2024). "To analyze the expression of BSG in pan-cancers, we used a web-based data mining approach based on GEPIA2." (PMID 38484369, 2024). "BSG mRNA expression level was significantly upregulated in seven cancer types, including ACC, ESCA, KICH, LIHC, PAAD, SKCM and THYM, when compared with corresponding normal tissues." (PMID 38484369, 2024). "Further comparisons of BSG, HSPA5 and ACE2, all of which are SARS-CoV-2 receptors and cofactors, we found the expression of BSG to be the highest across almost all kinds of cancer types and normal tissues." (PMID 38484369, 2024).